PRKAA1 (protein kinase AMP-activated catalytic subunit alpha 1)
Description:
Catalytic subunit of AMP-activated protein kinase (AMPK), an energy sensor protein kinase that plays a key role in regulating cellular energy metabolism. In response to reduction of intracellular ATP levels, AMPK activates energy-producing pathways and inhibits energy-consuming processes: inhibits protein, carbohydrate and lipid biosynthesis, as well as cell growth and proliferation. AMPK acts via direct phosphorylation of metabolic enzymes, and by longer-term effects via phosphorylation of transcription regulators. Regulates lipid synthesis by phosphorylating and inactivating lipid metabolic enzymes such as ACACA, ACACB, GYS1, HMGCR and LIPE; regulates fatty acid and cholesterol synthesis by phosphorylating acetyl-CoA carboxylase (ACACA and ACACB) and hormone-sensitive lipase (LIPE) enzymes, respectively (By similarity). Promotes lipolysis of lipid droplets by mediating phosphorylation of isoform 1 of CHKA (CHKalpha2). Regulates insulin-signaling and glycolysis by phosphorylating IRS1, PFKFB2 and PFKFB3 (By similarity). AMPK stimulates glucose uptake in muscle by increasing the translocation of the glucose transporter SLC2A4/GLUT4 to the plasma membrane, possibly by mediating phosphorylation of TBC1D4/AS160 (By similarity). Acts as a key regulator of glucose homeostasis in liver by phosphorylating CRTC2/TORC2, leading to CRTC2/TORC2 sequestration in the cytoplasm (By similarity). In response to stress, phosphorylates 'Ser-36' of histone H2B (H2BS36ph), leading to promote transcription (By similarity). Acts as a key regulator of cell growth and proliferation by phosphorylating FNIP1, TSC2, RPTOR, WDR24 and ATG1/ULK1: in response to nutrient limitation, negatively regulates the mTORC1 complex by phosphorylating RPTOR component of the mTORC1 complex and by phosphorylating and activating TSC2. Also phosphorylates and inhibits GATOR2 subunit WDR24 in response to nutrient limitation, leading to suppress glucose-mediated mTORC1 activation. In response to energetic stress, phosphorylates FNIP1, inactivating the non-canonical mTORC1 signaling, thereby promoting nuclear translocation of TFEB and TFE3, and inducing transcription of lysosomal or autophagy genes. In response to nutrient limitation, promotes autophagy by phosphorylating and activating ATG1/ULK1. In that process, it also activates WDR45/WIPI4. Phosphorylates CASP6, thereby preventing its autoprocessing and subsequent activation. In response to nutrient limitation, phosphorylates transcription factor FOXO3 promoting FOXO3 mitochondrial import (By similarity). Also acts as a regulator of cellular polarity by remodeling the actin cytoskeleton; probably by indirectly activating myosin. AMPK also acts as a regulator of circadian rhythm by mediating phosphorylation of CRY1, leading to destabilize it (By similarity). May regulate the Wnt signaling pathway by phosphorylating CTNNB1, leading to stabilize it (By similarity). Also has tau-protein kinase activity: in response to amyloid beta A4 protein (APP) exposure, activated by CAMKK2, leading to phosphorylation of MAPT/TAU; however the relevance of such data remains unclear in vivo (By similarity). Also phosphorylates CFTR, EEF2K, KLC1, NOS3 and SLC12A1. Regulates hepatic lipogenesis. Activated via SIRT3, represses sterol regulatory element-binding protein (SREBP) transcriptional activities and ATP-consuming lipogenesis to restore cellular energy balance. Upon stress, regulates mitochondrial fragmentation through phosphorylation of MTFR1L. Phosphorylates ALDH7A1 in response to cellular stress, such as hypoxia or ferroptotic stress, promoting ALDH7A1 recruitment to membranes.
Synonyms: AMPKa1; AMPK; AMPK alpha 1
Tractability: Small molecule: a drug acting on it is in phase 2 or 3 trials; a structure with a bound ligand is known; a high-quality ligand is known; it belongs to a druggable protein family. PROTAC: it is named in the literature on targeted protein degradation; UniProt records ubiquitination sites on it; ubiquitination databases record sites on it; its protein half-life has been measured; a small molecule that binds it is known.
Target class: CAMK protein kinase group; CAMK protein kinase AMPK subfamily; Protein Kinase; Enzyme; CAMK protein kinase CAMK1 family; Kinase
Chemical probes: BAY-3827 (high quality)
Safety:
Unwanted effects reported when the protein is acted on. In parentheses: how it was acted on, where the effect was seen, and who reports it.
heart disease (cardiovascular system; source: Force et al. (2011))
Gene: Protein-coding gene on chromosome 5 (40,759,389 to 40,798,374, reverse strand). Ensembl gene ENSG00000132356.
Subcellular location: Cytoplasm; Nucleus; Late endosome
Subcellular location (Human Protein Atlas): Nuclear speckles; Basal body; Cytosol; Primary cilium
Pathways (Reactome):
Autophagy: Macroautophagy
Immune System: AMPK-induced ERAD and lysosome mediated degradation of PD-L1(CD274)
Neuronal System: Activation of AMPK downstream of NMDARs
Signal Transduction: Energy dependent regulation of mTOR by LKB1-AMPK
Gene Ontology:
Molecular function: AMP-activated protein kinase activity; protein binding; protein kinase activity; protein serine kinase activity; protein serine/threonine kinase activity; [hydroxymethylglutaryl-CoA reductase (NADPH)] kinase activity; cAMP-dependent protein kinase activity; chromatin binding; histone H2BS36 kinase activity; tau protein binding; tau-protein kinase activity; ATP binding; protein-containing complex binding
Biological process: CAMKK-AMPK signaling cascade; cellular response to glucose starvation; cellular response to nutrient levels; cellular response to starvation; cellular response to stress; lipid droplet disassembly; motor behavior; negative regulation of hepatocyte apoptotic process; negative regulation of TORC1 signaling; neuron cellular homeostasis; positive regulation of autophagy; positive regulation of T cell activation; positive regulation of T cell mediated immune response to tumor cell; protein localization to lipid droplet; protein localization to membrane; protein localization to plasma membrane; regulation of vascular permeability; cellular response to calcium ion; cellular response to glucose stimulus; cellular response to oxidative stress; energy homeostasis; fatty acid homeostasis; glucose homeostasis; lipid biosynthetic process; negative regulation of apoptotic process; and 32 more
Cellular component: cytoplasm; cytosol; nuclear speck; nucleotide-activated protein kinase complex; nucleus; axon; dendrite; endoplasmic reticulum lumen; neuronal cell body; nucleoplasm; apical plasma membrane; chromatin; late endosome; protein-containing complex
Genetic constraint (gnomAD): Loss-of-function variants: 21 observed, 52.47 expected, observed/expected ratio (o/e) 0.4, 90% interval 0.28 to 0.58. The upper end of that interval is the gene's LOEUF score, 0.58, which puts it in group 2 of 6, group 1 being the genes least tolerant of losing a copy. Missense variants: 406 observed, 685.12 expected, observed/expected ratio (o/e) 0.59, 90% interval 0.55 to 0.64. Synonymous variants: 219 observed, 232.68 expected, observed/expected ratio (o/e) 0.94, 90% interval 0.84 to 1.05.
Homologues: Orthologues: chimpanzee PRKAA1 (100% identical), dog PRKAA1 (99% identical), pig PRKAA1 (99% identical), rat Prkaa1 (99% identical), mouse Prkaa1 (99% identical), rabbit PRKAA1 (99% identical), guinea pig PRKAA1 (98% identical), tropical clawed frog prkaa1 (90% identical), macaque PRKAA1 (86% identical), zebrafish prkaa1 (86% identical), Drosophila melanogaster Nuak (29% identical), Caenorhabditis elegans ZK524.4 (24% identical), and 4 more. Paralogues in human: PRKAA2 (76% identical), SIK2 (31% identical), SIK1 (31% identical), BRSK2 (30% identical), BRSK1 (30% identical), SIK3 (30% identical), MELK (29% identical), NUAK1 (28% identical), NUAK2 (28% identical), SNRK (27% identical), HUNK (24% identical), NIM1K (23% identical), and 5 more.
Diseases named in the same sentence as PRKAA1 in open-access papers:
PRKAA1 is named in the same sentence as 171 diseases in open-access papers, as found by Europe PMC text mining. Sharing a sentence is not in itself a finding about the gene and the disease. The quoted sentences say what the papers report.
breast carcinoma (27 papers, 2011 to 2024). "The PRKAA1 (protein kinase AMP-activated catalytic subunit alpha 1), which belongs to the Ser/Thr protein kinase family, was reported to mediate autophagy in multiple diseases, including diabetes, breast cancer, and cardiac hypertrophy 55-57." (PMID 37705752, 2023). "Evidence from TCGA database and GTEx projects indicated that the expression of PRKAA1 in gastric cancer tissue is higher, compared to normal stomach tissue, as well as it in breast cancer and esophageal squamous cell carcinoma." (PMID 30340465, 2018). "Most of the publications concerned about PRKAA1 polymorphisms focused on its significantly positive association with gastric cancer (GC), as well as on breast cancer, but there are also some negative results." (PMID 30340465, 2018). "The functions of PRKAA1, PTK2, and TSC2 in PI3K/signaling governing HER2+ breast cancer development and suppression by PGB-0-ol remain unknown and require further investigation." (PMID 38028209, 2023). "Thus, further studies should be performed to explore the role of PRKAA1 and RPS6KB1 in breast cancer development." (PMID 29769411, 2019). "Our result revealed that AITC did not affect the expression of PRKAA1 in MDA-MB-231 cells, indicating AITC may not inhibit MDA-MB-231 breast cancer cell growth." (PMID 29300316, 2018).
Obesity (26 papers, 2013 to 2025). Accumulation of substantial excess body fat. "In line with our results, mice with macrophage-specific deletion of the AMPKα1 subunit (Prkaa1) were found to be protected against high-fat diet-induced obesity and insulin resistance." (PMID 40945690, 2025). "The deletion of its PRKAA1 subunit can induce obesity and hepatic steatosis." (PMID 40400677, 2025).
gastric cancer (23 papers, 2015 to 2026). A primary or metastatic malignant neoplasm involving the stomach. "The miR-1273 family with the PRKAA1 gene forms the association recommended for gastric cancer diagnosis." (PMID 33801990, 2021). "The PRKAA1 rs13361707 T>C is the most widely studied polymorphism associated with gastric cancer risk." (PMID 34491229, 2021). "So far, a number studies have reported that PRKAA1 rs13361707 C/T polymorphism is associated with gastric, colon, and rectal cancers (especially gastric cancer)." (PMID 28978122, 2017). "A single nucleotide polymorphism (SNP) of the protein kinase catalytic subunit alpha-1 gene (PRKAA1) that confers susceptibility to gastric cancer (GC) was identified by genome-wide association in several case-control studies." (PMID 28978122, 2017). "Here, we evaluated the effects of interactions between H. pylori infection and PRKAA1 polymorphisms on gastric cancer risk in Koreans." (PMID 27726301, 2016). "Individuals with at least one variant allele of PRKAA1 rs10074991 or rs13361707 had a significantly increased risk of gastric cancer compared to the carriers with the homozygous wild‐type allele." (PMID 27726301, 2016). "Our results indicated that H. pylori infection, CagA status, and PRKAA1 polymorphisms were risk factors for gastric cancer in Koreans, and that the combination of two of these factors rather than their independent effects synergistically increased the risk." (PMID 27726301, 2016). "This study showed that HP infection, CagA status, and PRKAA1 polymorphisms are risk factors for gastric cancer in Koreans; specifically, the additive interaction between two of these factors increases gastric cancer risk." (PMID 27726301, 2016). "This study is the first to verify that CagA virulence factor‐related HP infection and PRKAA1 polymorphisms have significant effects on gastric cancer risk through the gene‐environment interactions." (PMID 27726301, 2016). "In order to evaluate the effects of the gene‐environmental interaction between PRKAA1 polymorphisms and HP infection on gastric cancer incidence, analysis of their independent and joint effects was performed." (PMID 27726301, 2016). "This study also verified that CagA status affects gastric cancer risk through its interaction with the PRKAA1 rs13361707 SNP." (PMID 27726301, 2016). "Genetic‐ and gene‐environmental effects of PRKAA1 rs10074997 and rs13361707 on the risk of gastric cancer were almost identical." (PMID 27726301, 2016). "In conclusion, this hospital‐based case–control study showed that the additive interaction between HP infection and PRKAA1 polymorphisms are significantly associated with gastric cancer risk in Koreans." (PMID 27726301, 2016). "Published data on the association between PRKAA1 rs13361707 T > C polymorphism and gastric cancer (GCa) susceptibility were inconclusive." (PMID 26485766, 2015). "Although several studies reported genetic polymorphisms in protein kinase AMP‐activated alpha 1 catalytic subunit (PRKAA1) and their associations with gastric cancer risk, few have evaluated associations between Helicobacter pylori infection and PRKAA1 gene‐environment interactions." (PMID 27726301, 2016). "However, few studies have evaluated the effects of interactions between PRKAA1 genetic polymorphisms and HP infection on gastric cancer incidence." (PMID 27726301, 2016). "However, this misclassification might lead to our results toward the null; nevertheless, we observed the significant independent and interactive association of HP infection and PRKAA1 polymorphisms on gastric cancer risk." (PMID 27726301, 2016). "In gastric cancer cells, PRKAA1 silencing significantly inhibits proliferation and promotes cell cycle arrest and apoptosis, in addition to reducing tumor growth in mouse models." (PMID 41596244, 2026). "PRKAA1 increases growth and blocks apoptosis in gastric cancer cells by inducing the JNK1 and Akt pathways." (PMID 38028209, 2023).
gastric cancer (continued). "Studies have shown that PRKAA1 increases proliferation and inhibits apoptosis of gastric cancer cells by activating the JNK1 and Akt pathways." (PMID 37056387, 2023). "PRKAA1 knockdown in gastric cancer cells showed a significant decrease in cell invasion and migration." (PMID 32724295, 2020). "In the evaluation of gene‐environment interactions between the PRKAA1 rs13361707 genotype and CagA status of HP infection as related to gastric cancer incidence, the RERI was 0.50 (95% CI: 0.30–0.70; P < 0.001), indicating a significant interaction." (PMID 27726301, 2016). "Based on cancer location, additive interaction between the PRKAA1 rs13361707 genotype and HP infection was shown to be significant in cardia gastric cancer (RERI, 1.25; 95% CI: 0.08–2.41; P = 0.036)." (PMID 27726301, 2016). "In subgroup analysis, we also evaluated the different effects of interactions between the PRKAA1 rs13361707 genotype and HP infection on gastric cancer incidence according to pathophysiological characteristics." (PMID 27726301, 2016). "Recently, several groups have published GWASs of gastric cancer focusing on single-nucleotide polymorphisms (SNPs), such as in a locus on chromosome 10q23 in the PLCE1 gene or in PRKAA1 at 5p13.1." (PMID 27121204, 2016). "In this hospital‐based case–control study, PRKAA1 genotypes were analyzed and H. pylori infection and CagA status were examined using a serologic method in 846 pairs of gastric cancer patients and controls matched for age and sex." (PMID 27726301, 2016). "In addition, it was observed that patients with gastric cancer with distant metastasis and advanced stages showed increased PRKAA1 expression." (PMID 41596244, 2026). "Recent studies have found that genetic variations in PRKAA1 have a close link with gastric cancer." (PMID 38633616, 2024). "Moreover, PRKAA1 enhances cell survival, colony formation, and glycolysis while inhibiting apoptosis by increasing the redox equilibrium in gastric cancer cells." (PMID 38028209, 2023). "Additionally, a recent meta‐analysis concerning PRKAA1 polymorphisms found that the PRKAA1 rs13361707 C allele was strongly associated with risk of noncardia gastric cancer." (PMID 27726301, 2016). "In gastric cancer cells, LINC00152 has been shown to modulate aerobic glycolysis through modulation of miR-139-5p and PRKAA1 expressions." (PMID 33123468, 2020). "PRKAA1 amplification and genetic alteration occur simultaneously along with other oncogenes, such as KRAS, in various solid tumors including gastric cancer." (PMID 27726301, 2016). "Genetic variations in other genes (e.g. KDM5A, DNAH7, PLCE1, PSCA, PRKAA1, MUC1) reported to be specifically associated with gastric cancer initiation and progression were not investigated in the current study." (PMID 27929383, 2016). "Previous works have suggested that polymorphisms in the PRKAA1 may be associated with the risk of non-cardiac gastric cancer (NCGC), but whether PRKAA1 polymorphisms are related to clinical pathologic characteristics of gastric cancer and its clinical outcome is largely unknown." (PMID 30253744, 2018).